H4C8 (H4 clustered histone 8)
Description:
Core component of nucleosome. Nucleosomes wrap and compact DNA into chromatin, limiting DNA accessibility to the cellular machineries which require DNA as a template. Histones thereby play a central role in transcription regulation, DNA repair, DNA replication and chromosomal stability. DNA accessibility is regulated via a complex set of post-translational modifications of histones, also called histone code, and nucleosome remodeling.
Synonyms: H4/H; H4FH; HIST1H4H
Tractability: Small molecule: a structure with a bound ligand is known. Antibody: its Gene Ontology location is reachable by antibodies, with high confidence. PROTAC: UniProt records ubiquitination sites on it; ubiquitination databases record sites on it; a small molecule that binds it is known.
Target class: Other nuclear protein
Gene: Protein-coding gene on chromosome 6 (26,277,609 to 26,285,638, reverse strand). Ensembl gene ENSG00000158406.
Subcellular location: Nucleus; Chromosome
Pathways (Reactome):
Gene expression (Transcription): B-WICH complex positively regulates rRNA expression; DNA methylation; ERCC6 (CSB) and EHMT2 (G9a) positively regulate rRNA expression; MLL4 and MLL3 complexes regulate expression of PPARG target genes in adipogenesis and hepatic steatosis; NoRC negatively regulates rRNA expression; PRC2 methylates histones and DNA; RNA Polymerase I Promoter Escape; RNA Polymerase I Promoter Opening; RUNX1 regulates genes involved in megakaryocyte differentiation and platelet function; RUNX1 regulates transcription of genes involved in differentiation of HSCs; Regulation of endogenous retroelements by KRAB-ZFP proteins; Regulation of endogenous retroelements by Piwi-interacting RNAs (piRNAs); Regulation of endogenous retroelements by the Human Silencing Hub (HUSH) complex; SIRT1 negatively regulates rRNA expression; Transcriptional regulation by small RNAs
Chromatin organization: CHD1 and CHD2 subfamily; CHD6, CHD7, CHD8, CHD9 subfamily; ChAHP complex assembly; HATs acetylate histones; HDACs deacetylate histones; HDMs demethylate histones; Interaction of NuRD complexes with transcription factors; NuRD complex assembly; PKMTs methylate histone lysines; RMTs methylate histone arginines
DNA Repair: Cleavage of the damaged purine; Cleavage of the damaged pyrimidine; Nonhomologous End-Joining (NHEJ); Processing of DNA double-strand break ends; Recognition and association of DNA glycosylase with site containing an affected purine; Recognition and association of DNA glycosylase with site containing an affected pyrimidine; Recruitment and ATM-mediated phosphorylation of repair and signaling proteins at DNA double strand breaks
Cell Cycle: Condensation of Prophase Chromosomes; Deposition of new CENPA-containing nucleosomes at the centromere; G2/M DNA damage checkpoint; Inhibition of DNA recombination at telomere; Packaging Of Telomere Ends
Developmental Biology: Activation of anterior HOX genes in hindbrain development during early embryogenesis; Chromatin modifications during the maternal to zygotic transition (MZT); Replacement of protamines by nucleosomes in the male pronucleus
and 20 more pathways
Gene Ontology:
Molecular function: protein binding; RNA binding; structural constituent of chromatin; DNA binding; protein heterodimerization activity
Biological process: negative regulation of megakaryocyte differentiation; nucleosome assembly; chromatin organization; protein localization to CENP-A containing chromatin; telomere organization
Cellular component: CENP-A containing nucleosome; chromosome, telomeric region; extracellular exosome; membrane; nucleoplasm; nucleosome; nucleus; protein-containing complex; extracellular region; chromosome
Genetic constraint (gnomAD): Loss-of-function variants: 7 observed, 3.7 expected, observed/expected ratio (o/e) 1.89, 90% interval 0.92 to 1.96. That is too few expected variants to judge how well the gene tolerates losing a copy. Missense variants: 165 observed, 111.25 expected, observed/expected ratio (o/e) 1.48, 90% interval 1.31 to 1.69. Synonymous variants: 85 observed, 37.62 expected, observed/expected ratio (o/e) 2.26.
Homologues: Paralogues in human: H4C1 (100% identical), H4C11 (100% identical), H4C12 (100% identical), H4C13 (100% identical), H4C14 (100% identical), H4C15 (100% identical), H4C16 (100% identical), H4C2 (100% identical), H4C3 (100% identical), H4C4 (100% identical), H4C5 (100% identical), H4C6 (100% identical), and 2 more.